SH3BP4 (SH3 domain binding protein 4)
Description:
May function in transferrin receptor internalization at the plasma membrane through a cargo-specific control of clathrin-mediated endocytosis. Alternatively, may act as a negative regulator of the amino acid-induced TOR signaling by inhibiting the formation of active Rag GTPase complexes. Preferentially binds inactive Rag GTPase complexes and prevents their interaction with the mTORC1 complex inhibiting its relocalization to lysosomes and its activation. Thereby, may indirectly regulate cell growth, proliferation and autophagy.
Synonyms: BOG25; TTP
Tractability: PROTAC: ubiquitination databases record sites on it; its protein half-life has been measured.
Gene: Protein-coding gene on chromosome 2 (234,952,017 to 235,055,714, forward strand). Ensembl gene ENSG00000130147.
Subcellular location: Membrane, clathrin-coated pit; Cytoplasmic vesicle, clathrin-coated vesicle; Nucleus
Pathways (Reactome):
Cellular responses to stimuli: Amino acids regulate mTORC1
Gene Ontology:
Molecular function: GDP-dissociation inhibitor activity; identical protein binding; protein binding; small GTPase binding
Biological process: amino acid import; cellular response to amino acid stimulus; negative regulation of cell growth; negative regulation of cell population proliferation; negative regulation of GTPase activity; negative regulation of TOR signaling; positive regulation of autophagy; protein localization to lysosome; regulation of catalytic activity; actin filament organization; Rho protein signal transduction
Cellular component: cytoplasm; extracellular exosome; clathrin-coated pit; clathrin-coated vesicle; nucleus
Genetic constraint (gnomAD): Loss-of-function variants: 33 observed, 67.09 expected, observed/expected ratio (o/e) 0.49, 90% interval 0.37 to 0.66. The upper end of that interval is the gene's LOEUF score, 0.66, which puts it in group 2 of 6, group 1 being the genes least tolerant of losing a copy. Missense variants: 1,126 observed, 1,296.1 expected, observed/expected ratio (o/e) 0.87, 90% interval 0.83 to 0.91. Synonymous variants: 551 observed, 562.34 expected, observed/expected ratio (o/e) 0.98, 90% interval 0.91 to 1.05.
Homologues: Orthologues: chimpanzee SH3BP4 (99% identical), macaque SH3BP4 (99% identical), dog SH3BP4 (92% identical), guinea pig SH3BP4 (92% identical), rat Sh3bp4 (92% identical), mouse Sh3bp4 (92% identical), pig SH3BP4 (92% identical), rabbit SH3BP4 (88% identical), tropical clawed frog sh3bp4 (73% identical), zebrafish sh3bp4a (72% identical), zebrafish sh3bp4 (65% identical). Paralogues in human: MACC1 (37% identical).
Diseases named in the same sentence as SH3BP4 in open-access papers:
SH3BP4 is named in the same sentence as 28 diseases in open-access papers, as found by Europe PMC text mining. Sharing a sentence is not in itself a finding about the gene and the disease. The quoted sentences say what the papers report.
adenoma (2 papers, 2019 to 2025). A neoplasm arising from the epithelium. "Studies have shown that the loss of SH3BP4 increases the number of intestinal stem cells and Paneth cells in mice, and accelerates the development of adenomas in Apcmin mice." (PMID 40414942, 2025). "This was accompanied by upregulated expression of Wnt targets Axin2 and Myc in ApcminSh3bp4 cKO adenomas, suggesting that Wnt signaling is hyperactivated upon Sh3bp4 deletion." (PMID 30811977, 2019). "We show that the loss of Sh3bp4 increases ISC and Paneth cell numbers in murine intestine and accelerates adenoma development in Apcmin mice." (PMID 30811977, 2019). "Because the loss of Sh3bp4 alone caused ISC expansion, we further analyzed the stem cell marker Lgr5 expression in Apcmin and ApcminSh3bp4 cKO adenomas." (PMID 30811977, 2019). "Consistent with the Sh3bp4 cKO phenotype, a significant increase in Lgr5-expressing stem cells was observed in the ApcminSh3bp4 cKO adenomas." (PMID 30811977, 2019). "RNAscope analysis of Apcmin intestine showed upregulation of Sh3bp4 in adenomas with aberrant Wnt activation, suggesting that Sh3bp4 expression is modulated by Wnt signaling." (PMID 30811977, 2019).
Alzheimer disease (2 papers, 2023 to 2025). A progressive, neurodegenerative disease characterized by loss of function and death of nerve cells in several areas of the brain leading to loss of cognitive function such as memory and language. "In contrast, SH3BP4 showed an association with nerve tibial tissue at non-suggestive levels for Alzheimer’s Disease." (PMID 37848535, 2023).
melanoma (2 papers, 2022 to 2025). A malignant, usually aggressive tumor composed of atypical, neoplastic melanocytes. "In a cohort study, the authors identified the tumor suppressor SH3BP4 as a biomarker for melanoma using whole-set genomic association analysis." (PMID 40414942, 2025). "Results from both single-marker analysis of rs77480547 and the downstream gene-based analysis implicate SH3BP4 (SRC homology 3 domain binding protein 4) as a candidate melanoma prognostic marker." (PMID 36741706, 2022). "The observed effect of miR-125b on melanoma tumor growth has been proposed to be by modulating SH3BP4 expression, suggesting the contributing role of this candidate gene in melanoma progression." (PMID 36741706, 2022). "While there has not been a study to systematically investigate the direct effect of SH3BP4 in the context of melanoma progression, a recent report identified SH3BP4 as a novel pigmentation gene that is inversely regulated by a validated melanoma prognostic marker miR-125b." (PMID 36741706, 2022). "Our study provides suggestive evidence of novel melanoma germline prognostic markers, implicating two candidate genes: an oncogene MELK and a tumor suppressor SH3BP4, both previously suggested to affect CM progression." (PMID 36741706, 2022).
osteoarthritis (2 papers, 2021 to 2025). A noninflammatory degenerative joint disease occurring chiefly in older persons, characterized by degeneration of the articular cartilage, hypertrophy of bone at the margins and changes in the synovial membrane. "Sh3bp4 thus represents an osteoarthritis susceptibility gene, the deletion of which accelerates joint damage." (PMID 33473114, 2021).
Arthritis (1 paper, 2021). Inflammation of a joint. "The top-ranked genes associated with arthritis and skeletal disease in humans were Pitx1, coiled-coil domain containing 6 (Ccdc6), HECT and RLD domain containing E3 ubiquitin protein ligase family member 1 (Herc1), nebulette (Nebl), Sh3bp4, and Zfp341." (PMID 33473114, 2021).
breast carcinoma (1 paper, 2017). "Totally 15 breast cancer risks genes were obtained (Benjamini & Hochberg FDR < 0.05) and 6 of them (FAM84B, AAGAB, RPS25, SH3BP4, KRT80, TANK) showed the most significant correlation with the patient survival." (PMID 28621677, 2017).
colon cancer (1 paper, 2022). "SH3BP4 is a gene paralog with approximately 50% shared nucleotide sequences with MACC1 (Metastasis-Associated In Colon Cancer Protein 1), an independent colon cancer prognostic marker." (PMID 36741706, 2022).
colorectal cancer (1 paper, 2019). A primary or metastatic malignant neoplasm that affects the colon or rectum. "Loss of Sh3bp4 exacerbates the Apcmin tumor phenotype through hyperactivation of Wnt signaling, suggesting its tumor suppressive role in colorectal cancer." (PMID 30811977, 2019). "In addition, the upregulated expression of SH3BP4 was also observed in human colorectal cancer (CRC) tissues and the Wnt-activated CRC cell lines." (PMID 30811977, 2019).
diabetic retinopathy (1 paper, 2022). "The SH3 domain-binding protein 4 (SH3BP4) is a negative regulator of amino acid-Rag GTPase-mTORC1 signaling and is related to diabetic retinopathy." (PMID 35681846, 2022).
glioblastoma (1 paper, 2025). The most malignant astrocytic tumor (WHO grade IV). "In another sequencing study, the authors found that SH3BP4 was down-regulated in glioblastoma cultured under neuroglobular formation conditions." (PMID 40414942, 2025).
Insulin resistance (1 paper, 2025). Increased resistance towards insulin, that is, diminished effectiveness of insulin in reducing blood glucose levels. "Intriguingly, our findings suggest that only certain obesity-related outcomes, perhaps those more closely tied to metabolic disruptions such as insulin resistance and ectopic fat, are causally associated to SH3BP4 methylation, while others closely related, such as BMI, are not." (PMID 40355419, 2025).
intestinal tumor (1 paper, 2019). "Deletion of Sh3bp4 increases stem cell numbers and accelerates intestinal tumor development in mice." (PMID 30811977, 2019). "Sh3bp4 cKO mice were crossed to the intestinal tumor model Apcmin mice (ApcminSh3bp4 cKO)." (PMID 30811977, 2019).
laryngeal carcinoma (1 paper, 2025). Carcinoma that arises from the laryngeal epithelium. "This intricate interplay between genetic variations within SH3BP4 and miRNA-mediated regulatory mechanisms may have significant implications for understanding the molecular basis of laryngeal cancer progression and overall patient survival outcomes." (PMID 40414942, 2025).
Obesity (1 paper, 2025). Accumulation of substantial excess body fat. "To discern the potential causal relationship between the 14 obesity-related variables and both SH3BP4 methylation and mtDNAq, we employed an ICE FALCON analysis for the complete MZ twin pairs in the cohort." (PMID 40355419, 2025). "Leveraging our data on MZ twin pairs, we identified potentially causal associations from mtDNAq and obesity-related outcomes to SH3BP4 methylation in adipose tissue." (PMID 40355419, 2025). "Obesity-related variables that associated exclusively with SH3BP4 methylation included elevated blood triglyceride levels, hsCRP, fasting glucose levels, and systolic blood pressure." (PMID 40355419, 2025). "The link we identified between the mtDNAq-associated methylation site in SH3BP4 and various obesity-related outcomes, particularly those assessing insulin sensitivity and body fat composition, implies a potential role of mtDNAq-induced methylation in the etiology of obesity." (PMID 40355419, 2025). "Despite this, we demonstrate that both mtDNAq as well as specific obesity-related outcomes may be causal to DNA methylation at SH3BP4, via shared or independent molecular pathways." (PMID 40355419, 2025). "Additionally, we find that 14 out of the 35 obesity-related traits display significant associations with both SH3BP4 methylation and mitochondrial DNA quantity in adipose tissue." (PMID 40355419, 2025). "Our findings underscore the impact of mitochondrial DNA quantity on DNA methylation and expression of the SH3BP4 gene within adipose tissue, with potential implications for obesity." (PMID 40355419, 2025). "Here, the authors use Finnish twin data to link obesity-related changes in mitochondrial DNA quantity with the methylation and expression of SH3BP4 in adipose tissue." (PMID 40355419, 2025). "Nevertheless, the discrepancy warrants further investigation into the pathways that result in changes in SH3BP4 methylation in the context of obesity." (PMID 40355419, 2025).
skin cancer (1 paper, 2022). "We found that in skin cancer, both MELK and SH3BP4 were significantly overexpressed in primary tumor compared to adjacent normal, suggesting its role in tumor initiation." (PMID 36741706, 2022).
tumor (7 papers, 2019 to 2025). "There was mRNAs downregulation of tumor suppressors such as SH3BP4 and DNPEP, which influence oncogenesis via the amino acid-induced TOR signaling and PAK5–DNPEP–USP4 pathway, respectively." (PMID 36354672, 2022). "SH3BP4 is a potential tumor suppressor, and its methylation is related to impaired insulin signaling." (PMID 34635168, 2021). "Transcriptomic analysis of human CRC patients further confirmed the increased expression of SH3BP4 in tumor samples." (PMID 30811977, 2019). "SH3BP4 has been previously suggested as a potential tumor suppressor gene in multiple human cancers, including breast, renal, and non-small-cell lung cancers with a high frequency of deletion." (PMID 30811977, 2019). "SH3BP4 is also involved in cell migration and invasion, suggesting that it may be involved in remodeling the tumor microenvironment as well as immune escape mechanisms." (PMID 40414942, 2025). "Besides, SH3BP4 negatively regulates Wnt signaling via modulating β-catenin’s subcellular localization, thus suppressing tumor development." (PMID 36211385, 2022). "SH3BP4 is considered as a tumor suppressor that functions in the amino acid-mTORC1 pathway." (PMID 36354672, 2022). "Our data uncover the tumor-suppressive role of SH3BP4 that functions as a negative feedback regulator of Wnt signaling through modulating β-catenin’s subcellular localization." (PMID 30811977, 2019).
cancer (5 papers, 2019 to 2025). A tumor composed of atypical neoplastic, often pleomorphic cells that invade other tissues. "It is worth noting that SH3BP4 gene locus is often either deleted in many human cancers, or there is a loss of heterozygosity." (PMID 36354672, 2022). "Our findings provide the mechanistic insight into the role of Sh3bp4 in ISCs and cancer by regulating Wnt/β-catenin signaling." (PMID 30811977, 2019). "Targeting SH3BP4 could lead to the development of novel treatments aimed at disrupting cancer-specific pathways, potentially improving treatment efficacy and patient outcomes in OSCC." (PMID 40414942, 2025). "Furthermore, methylation patterns in SDMCs influenced the transcription of several genes (MEIS1, MIA3, PCDHAC2, SH3BP4, and ATP8B1) involved in well-known cancer-related pathways and cancer hallmarks (FDR < 0.05)." (PMID 36348462, 2022). "It is conceivable that SH3BP4 inactivation may contribute to an alternative Wnt activating mechanism in certain CRC subtypes, which could offer a new therapeutic strategy for targeting Wnt signaling in cancer." (PMID 30811977, 2019).
infection (3 papers, 2019 to 2024). The state of being infected such as from the introduction of a foreign agent such as serum, vaccine, antigenic substance or organism. "We found that SH3BP4, ADAM9, and TMEM2 display enhanced binding to CoV2-RBD compared to CoV-RBD, suggesting that specific amino acid changes in CoV2-RBD enable SARS-CoV-2 to bind these host factors thereby potentially promoting infection." (PMID 38777146, 2024). "Interestingly, SH3BP4 and ACAP1, which have been shown to promote TfnR endocytosis and recycling by binding to the receptor, were also recruited to infection sites in a T3SS-dependent manner." (PMID 31242273, 2019).
SH3BP4 also shares sentences with these, for which no sentence is quoted: autism (1 paper); behavioral disorders (1); brachydactyly (1); diabetes (1); Hypercholesterolemia (1); Intellectual disability (1); liver cancer (1); microcephaly (1); renal carcinoma (1); skeletal disease (1).